SULF1 (sulfatase 1)
Diseases named in the same sentence as SULF1 in open-access papers (continued):
Sharing a sentence is not in itself a finding about the gene and the disease.
gastric tumours (1 paper, 2015). "The ability of Sulf1 to inhibit the stabilization of β-catenin when re-expressed in gastric tumours indicates that, in this context, Sulf1 inhibits canonical Wnt signalling." (PMID 25681501, 2015).
glaucoma (1 paper, 2021). Increased pressure in the eyeball due to obstruction of the outflow of aqueous humor. "TLL1 and SULF1 have no reported associations with glaucoma or IOP regulation, however, both genes encode proteins associated with fibrosis and an epithelial to mesenchymal transition (EMT) which shows similar phenotypic changes to that observed in POAG." (PMID 34440692, 2021).
Granuloma (1 paper, 2024). A compact, organized collection of mature mononuclear phagocytes, which may be but is not necessarily accompanied by accessory features such as necrosis. "Then the upregulated expression of SULF1 in the lung and blood samples may be closely related to angiogenesis in granulomas and pathological changes of lung epithelial cells induced by tuberculosis." (PMID 39023413, 2024).
HCMV infection (1 paper, 2018). "Accordingly, we hypothesized that ADD1 and SULF1 methylation were related to HCMV infection and induction of EH in the Kazakh population." (PMID 29752343, 2018).
high blood pressure (1 paper, 2013). "SULF1 and SULF2 (another protein in this family) double knockout mice show impairment in skeletal development, but whether they display high blood pressure has never been explored." (PMID 23325143, 2013).
infertile (1 paper, 2015). "Our research is the first study that investigates SULF1 role in infertility." (PMID 26131010, 2015).
invasive carcinoma (1 paper, 2007). A carcinoma that is not confined to the epithelium, and has spread to the surrounding stroma. "In situ hybridization localized expression of SULF1 to tubular structures, likely representing invasive carcinoma." (PMID 17460759, 2007).
ischemia (1 paper, 2021). A hypoperfusion of the BLOOD through an organ or tissue caused by a PATHOLOGIC CONSTRICTION or obstruction of its BLOOD VESSELS, or an absence of BLOOD CIRCULATION. "To examine if some changes in cell signalling or Sulf1/Sulf2 levels during in vivo ischemia were also apparent during in vitro hypoxia, we exposed HMec1 human endothelial cells to 100 μM and 300 μM CoCl2 chemical hypoxia for different lengths of time to examine changes in VEGF levels." (PMID 34789772, 2021). "Human myocardial infarctions in this study showed variable levels of SULF1/SULF2 increases in different patients or different parts of the same heart that could relate to the length of ischemia and distance from the ischemic injury." (PMID 34789772, 2021).
laryngeal tumors (1 paper, 2020). "SULF1 has the highest expression in laryngeal tumors which are significantly higher than in oropharynx (p = 0.028)." (PMID 33585200, 2020).
metastatic cancer (1 paper, 2025). A carcinoma which has spread from the original site of growth to another anatomic site. "The results showed that the expression levels of CLOCK, along with CBX5, CHN1, CNN3, FNDC1, PALLD, and SULF1, were significantly elevated in metastatic cancer tissues compared to primary cancer tissues." (PMID 41350567, 2025).
myocardial hypertrophy (1 paper, 2021). "It's worth noting that there is no relevant report about the roles of COMP, FMOD, AEBP1 and SULF1 in HOCM or even myocardial hypertrophy, implying the need for further exploration." (PMID 34362365, 2021).
myocardial infarction (1 paper, 2021). Gross necrosis of the myocardium, as a result of interruption of the blood supply to the area, as in coronary thrombosis. "In vitro hypoxia of endothelial cells in this study clearly demonstrated the modulation of both Sulf1/Sulf2 and some growth factors that may help explain in vivo changes observed upon myocardial infarction or disease." (PMID 34789772, 2021). "Many myocardial samples generally showed increased SULF1/SULF2 expression in ischemic hearts following single or multiple myocardial infarctions irrespective of their age." (PMID 34789772, 2021).
nephrosis (1 paper, 2019). Pathological processes of the KIDNEY without inflammatory or neoplastic components. "Not only is Knockdown of Sulf1, Sulf2a, and Sulf2b causative of eGFP-DBP fusion protein loss of Tg(l-fabp:eGFP-DBP) larvae indicative of proteinuria, but also it may function as a second hit to the GFB in the PAN nephrosis model." (PMID 31428635, 2019).
neuroblastoma (1 paper, 2022). Neuroblastoma (NB) is the most common solid, extracranial childhood tumor. "SULF1 expression in fibroblast cells is distinctly higher compared with all the cancer cell lines but SULF2 expression is the highest in cell lines from neuroblastoma, HNSC, and other cancers." (PMID 36428645, 2022).
Obesity (1 paper, 2013). Accumulation of substantial excess body fat. "Obesity might be a confounder explaining the relation between methylation levels of the SULF1 gene and EH." (PMID 23325143, 2013). "Moreover, it is also possible that SULF1 gene methylation is a mediator of obesity related EH." (PMID 23325143, 2013).
osteosarcoma (1 paper, 2023). A usually aggressive malignant bone-forming mesenchymal neoplasm, predominantly affecting adolescents and young adults. "This regulation of EZH2/SULF1 axis was also observed in the other sarcoma cells such as osteosarcoma cell lines." (PMID 36622753, 2023).
prostate tumors (1 paper, 2020). "Furthermore, SULF1 protein levels were found to be higher in the stromal compartment of primary prostate tumors compared to their healthy counterparts, which is consistent with our observations in bone metastatic sites." (PMID 32413029, 2020).
sarcoma (1 paper, 2023). A usually aggressive malignant neoplasm of the soft tissue or bone. "(G) Prognostic correlation of survival analyses of sarcoma patients with high and low SULF1 levels." (PMID 36622753, 2023).
skin cutaneous melanoma (1 paper, 2023). "Interestingly, high TFCP2 expression (p = 0.049) and low SULF1 expression (p = 0.039) significantly correlated with poorer overall survival outcomes for patients with skin cutaneous melanoma." (PMID 37061003, 2023).
testicular cancer (1 paper, 2011). A primary or metastatic malignant neoplasm that affects the testis. "Finally, SULF1 and SULF2 were simultaneously overexpressed in 6 cancer types: brain, breast, head and neck, renal, skin and testicular cancers." (PMID 21599997, 2011).
tuberculosis (1 paper, 2024). A chronic, recurrent infection caused by the bacterium Mycobacterium tuberculosis. "For example, a panel of markers, such as TYMP, LAP3, ANXA, and SULF1, along with traditional tuberculosis‐related symptoms such as persistent cough, weight loss, and fever, can be used to differentiate between patients with cancer, post‐SARS‐CoV‐2 infection, and those at risk for tuberculosis." (PMID 39023413, 2024). "The results of ROC showed that TYMP (AUC = 0.964), LAP3 (AUC = 0.914), ADGRL2 (AUC = 0.98), SIL1 (AUC = 0.936), LMO7 (AUC = 0.856), SULF1 (AUC = 0.96), ANXA3 (AUC = 0.798), and PACSIN3 (AUC = 0.747) had high accuracy in predicting tuberculosis." (PMID 39023413, 2024).
viral infection (1 paper, 2010). "In this population-based study, we found nine genes/regions associated with CIN3/cancer, 6 of which remained significant at a FDR≤0.2 – three DNA repair genes (GTF2H4, DUT, and DMC1) and three viral infection and cell entry related genes (OAS3, SULF1, and IFNG)." (PMID 20084279, 2010).
Wilms tumor (1 paper, 2021). An embryonal neoplasm characterized by the presence of epithelial, mesenchymal, and blastema components. "Further support for the connection between SULF2/SULF1 and proteinuria was obtained from children with Wilms’ tumor." (PMID 33540508, 2021).
tumor (79 papers, 2007 to 2026). "The results indicated that WT SULF1, associated with full sulfatase activity inhibited tumor development, consistent to what was observed in vitro culture." (PMID 36622753, 2023). "Subsequent single-cell RNA-seq analysis revealed that the high expression of SULF1 primarily originated from tumor-associated fibroblasts." (PMID 37985153, 2023). "In contrast, multiple genes were upregulated in tumour-associated myofibroblasts compared to their control counterparts, including SULF1, COL11A1 and LRRC15." (PMID 36720863, 2023). "These heparan sulfate editing enzymes were considered largely functional redundant but single-cell RNAseq (scRNAseq) shows that SULF1 is secreted by cancer-associated fibroblasts in contrast to the SULF2 derived from tumor cells." (PMID 36428645, 2022). "High SULF1 mRNA expression in a tumor is associated with poor PFI in early stage patients (HR = 2.327, p = 0.023) but not in late-stage patients (HR = 1.034, p = 0.842)." (PMID 36428645, 2022). "Our results also suggest that SULF1+ cells in the stroma are more abundant in node-positive tumors which is in line with recent papers associating low tumor/stroma ratio or the presence of CAF with poor HNSC survival outcomes." (PMID 36428645, 2022). "SULF1 has also been linked to tumour suppressor functions as it has been reported to be downregulated in some cancers." (PMID 32398079, 2020). "Expressions of MMP12 and SULF1 were associated with tumor progression or metastasis in COAD, HNSC, LUAD, and LUSC." (PMID 33324676, 2020). "SULF1 has been associated with tumor suppressor effects in various models of cancer, whereas SULF2 dysregulation was in relation with protumorigenic actions." (PMID 21599997, 2011). "Taken together, these studies reaffirm our bioinformatics-based analysis and suggest that these extracellular matrix genes (CDH3, COL11A1, COL1A1, COL17A1, KRT19, ITGA2, LAMC2, and SULF1) are highly associated with PDAC tumor carcinogenesis and peritoneal metastasis." (PMID 39682235, 2024). "To assert SULF1 functions as a tumor suppressor, we considered not only its direct impact in our 3D tricultures but also its expression levels by cell lines and metastatic tissues, in addition to the influence of tumor-associated cells regulating SULF1 and HSPG2 expression." (PMID 32413029, 2020). "However, the activity of Heparin Sulfate Proteoglycans (HSPGs), a proteoglycan which is known to regulate various genes associated with tumor metastasis, is controlled by Sulf-1." (PMID 27626699, 2016). "Although Sulf1 inhibits angiogenesis and tumorigenesis in vivo, a number of clinical studies have found that higher Sulf1 mRNA levels have been associated with tumor tissue compared to normal pancreas in relatively small cohorts of PDAC patients." (PMID 25105093, 2014). "Moreover, SULF1 has been linked with a tumor suppression function and its expression was ubiquitous but reportedly downregulated in most of cancer cell lines." (PMID 21214932, 2011). "In order to understand the effects of Sulf1+ CAFs on tumor cell invasion, we performed spheroid coculture assays using GFP‐tagged Cal33 and SCC35 cells embedded in Matrigel." (PMID 41549062, 2026). "The fact that they are produced by different cell types suggests that the SULF1 will regulate the local microenvironment of the CAF more than the SULF2 which will be active closer to the tumor cells." (PMID 41549062, 2026). "Taken together, the impact of SULF1 in the TME is highly context-dependent on the tumor type, expression in stromal cells, the mechanism of SULF1 gene activation, and hypoxia." (PMID 41373732, 2025).
tumor (continued). "Sulfation patterns are particularly important in mediating heparin’s anticancer effects, with SULF1, a heparan-sulfate-desulfating enzyme, exhibiting tumor suppressor properties." (PMID 40143176, 2025). "There is a tumor suppressor role for SULF1, being an extracellular sulfatase that removes 6-O-sulfate groups from heparan sulfate (HS) chains, thereby reducing the activity of HS-binding growth factors such as FGF2, VEGF, amphiregulin, HB-EGF, and HGF." (PMID 41373732, 2025). "The desulfating enzyme SULF1 has been identified as a tumor suppressor, further emphasizing the importance of sulfation balance in cancer biology." (PMID 40143176, 2025). "Sulf-2 is secreted in the tumor tissues primarily by cancer cells while Sulf-1 is supplied to the tumor microenvironment by CAF cells." (PMID 38825040, 2024). "In order to further validated the role of CAFs-derived SULF1 in GC, we conducted the lung metastasis model and subcutaneous tumor formation model in nude mice by inoculating HGC27 cells with indicated treatments." (PMID 38438372, 2024). "Some studies reported that SULF1 was downregulated and inhibited tumor progression in several cancers." (PMID 38438372, 2024). "The clinicopathological information of above 80 GC patients showed high SULF1 expression was related to large tumor size, poor tumor differentiation, lymph node metastasis and advanced tumor stage in GC patients." (PMID 38438372, 2024). "LAMC2, for instance, plays a crucial role in cancer cell invasion and metastasis, while SULF1 is involved in multiple signaling pathways critical for tumor progression." (PMID 39850570, 2024). "High NEAT expression promoted SULF1 expression by binding to miR-376b-3p, promoting tumor cell growth and apoptosis." (PMID 38077434, 2023). "We have documented that cancer-associated fibroblasts (CAF) supply Sulf-1 to HNSC tumors, which explains the cancer cell–tumor discrepancy." (PMID 37958342, 2023). "Broadly, SULF1 is epigenetically silenced in many cancer types and forced expression decreases tumor cell proliferation, migration, and invasion." (PMID 37061003, 2023). "(I) BALB/c nude mice were subcutaneously inoculated stable cell lines with vector (n=5), WT SULF1(WT; n=5), and enzymatic inactive SULF1 (CA mutant; n=6), tumor growth was plotted at the indicated days after transplantation." (PMID 36622753, 2023). "SULF1 expression is significantly higher in fibroblasts compared with tumor epithelial cells in terms of both percent positivity and expression; in contrast, SULF2 expression has the opposite trend." (PMID 36428645, 2022). "Four studies showed >2-fold increase in SULF1 protein in tumor tissues with the highest fold-change observed in HNSC (log2FC = 1.59, FDR < 0.001)." (PMID 36428645, 2022). "Whereas SULF-2 plays tumor-promoting roles in several cancer types by supporting the signaling of HS-binding growth factors, SULF-1 is generally considered an onco-suppressor albeit an oncogenic role in hepatocarcinogenesis has been reported." (PMID 36359323, 2022). "In summary, SULF2 expression increases in multiple malignancies but less consistently than SULF1, which uniformly increases in the tumor tissues and negatively impacts survival in several types of cancer even though its expression in cancer cells is low." (PMID 36428645, 2022). "SULF1 is significantly upregulated in tumor tissues of 10 of the 14 studies of which 9 show >2-fold upregulation." (PMID 36428645, 2022). "High SULF1 expression was also associated with poorer prognosis, hence more advanced TNM (Tumor, Node, Metastasis) stages, and was correlated with higher CA19-9 levels, despite smaller tumor size." (PMID 34249755, 2021). "Increased SULF1 expression levels in patients with distant metastasis, advanced stages of the tumor, as well as colorectal CSC-enriched spheroids indicate that the levels of SULF1 expression is being increased by tumor progression in CRC." (PMID 34107956, 2021).
tumor (continued). "Expression of both HSPG2 and SULF1 was concentrated in αSMA-rich stroma near PCa tumor nests, where infiltrating pro-tumor TAMs also were present." (PMID 32413029, 2020). "In contrast to hypermethylation, hypomethylation of sulfatase 1 (SULF1) and matrix metalloproteinase 2 (MMP2) promoters was observed to be associated with the enrichment of F. nucleatum in our HNSCC tumor tissues." (PMID 33218162, 2020). "In mCRPC, although SULF1 is nearly silenced in cancer cells, the macrophage infiltrated tumor stroma continues to produce SULF1 and perlecan." (PMID 32413029, 2020). "Quantification of the SULF1 mRNA shows that approximately 95% of the signal is confined to αSMA+ activated fibroblasts, and is nearly undetected in E-cad+ tumor cells." (PMID 32413029, 2020). "Downregulation of miR-516, a tumor suppressive miRNA, decreases metastasis by decreasing sulfatase-1 expression leading to a decrease in the Wnt-Beta catenin pathway." (PMID 30546829, 2018). "In conclusion, our study found that increased SULF1 expression is significantly predictive of more advanced tumor stage and poorer metastasis-free survival and disease-specific survival in patients with both UTUC and UBUC." (PMID 28525382, 2017). "The effects of SULF1 as a tumor suppressor have been identified in HCC for mediating the inhibition of HS-dependent receptor tyrosine kinase signaling in in vitro and in vivo mouse xenografts." (PMID 28525382, 2017). "Modification involves removal of the sulfo group at the C6 position in regions of the HS chain by SULF1/2 to reduce signaling by heparin-dependent growth factors and tumor growth." (PMID 28672878, 2017). "After univariate and multivariate analysis in metastasis-free survival (MeFS), high SULF1 expression, tumor multifocality, nodal metastasis, high histological grade, vascular and perineural invasion remained as independently significant prognosticators." (PMID 28525382, 2017). "SULF1 controls the sulfation status of heparan sulfate proteoglycans and plays a role in tumor growth and metastasis, while its role is unexplored in UC." (PMID 28525382, 2017). "It was reported that sulfatase 1 (SULF1) played an important role in the progression of HCC tumor via augmentation of the TGF-beta pathway." (PMID 28819584, 2017). "The desulfation action of Sulf-1 is known to inhibit many signaling pathways involved in tumor cell differentiation, proliferation, migration, invasion and lymphatics metastasis." (PMID 27626699, 2016). "Our results showed reduction in cell proliferation in the Sulf-1 up-regulated cells compared to the controls, confirming the tumor suppressor role of Sulf-1 as reported in other studies." (PMID 27626699, 2016). "The experiment in vivo further showed that up-regulation of Sulf-1 with the attendant downregulation of mesothelin delayed tumor growth and decreased lymph node metastasis." (PMID 27626699, 2016). "What is surprising is that despite their seemingly identical function, there are data to support the conclusion that Sulf-1 suppresses tumour growth while Sulf-2 promotes tumour growth." (PMID 27408707, 2016). "The tumor suppressor function of Sulf-1 and the tumor promoter role of Msln have been confirmed in this study, both in vitro and in vivo." (PMID 27626699, 2016). "Although it is generally agreed that the function of Sulf-1 and -2 is to selectively remove 6-O sulphates from heparan sulphate chains, the impact of these two extracellular sulphatases on tumour growth and progression remains controversial." (PMID 27408707, 2016). "An overview of SULF gene expression in human cancers indicates that although SULF1 is sometimes downregulated, more often SULF1 and/or SULF2 are overexpressed in tumours, which can be associated with a worse prognosis." (PMID 25681501, 2015). "A subsequent study showed that restoration of Sulf1 expression leads to decreased tumor growth, angiogenesis, and enhanced the efficacy of chemotherapeutic agents such as cisplatin." (PMID 25105093, 2014).